CD52 (CD52 molecule)
Description:
May play a role in carrying and orienting carbohydrate, as well as having a more specific role.
Synonyms: He5; CDW52; EDDM5
Tractability: Small molecule: a structure with a bound ligand is known. Antibody: an approved drug acts on it; its Gene Ontology location is reachable by antibodies, with high confidence; UniProt places it where antibodies can reach, with medium confidence; UniProt predicts a signal peptide or a membrane-spanning region.
Target class: Surface antigen
Gene: Protein-coding gene on chromosome 1 (26,317,958 to 26,320,523, forward strand). Ensembl gene ENSG00000169442.
Subcellular location: Cell membrane
Pathways (Reactome):
Metabolism of proteins: Post-translational modification: synthesis of GPI-anchored proteins
Gene Ontology:
Molecular function: protein binding
Biological process: positive regulation of cytosolic calcium ion concentration; respiratory burst
Cellular component: extracellular region; membrane; plasma membrane; sperm midpiece
Genetic constraint (gnomAD): Loss-of-function variants: 2 observed, 2.7 expected, observed/expected ratio (o/e) 0.74, 90% interval 0.29 to 1.79. That is too few expected variants to judge how well the gene tolerates losing a copy. Missense variants: 62 observed, 79.09 expected, observed/expected ratio (o/e) 0.78, 90% interval 0.64 to 0.97. Synonymous variants: 24 observed, 29.25 expected, observed/expected ratio (o/e) 0.82, 90% interval 0.59 to 1.15.
Homologues: Orthologues: chimpanzee CD52 (98% identical), macaque CD52 (87% identical), dog CD52 (56% identical), rat Cd52 (51% identical), pig CD52 (49% identical), mouse Cd52 (44% identical).
Diseases named in the same sentence as CD52 in open-access papers:
CD52 is named in the same sentence as 140 diseases in open-access papers, as found by Europe PMC text mining. Sharing a sentence is not in itself a finding about the gene and the disease. The quoted sentences say what the papers report.
chronic lymphocytic leukemia (33 papers, 2008 to 2025). "Its associated monoclonal antibodies, anti-CD52, including alemtuzumab and analogues, are intended for treatment of multiple sclerosis and B cell chronic lymphocytic leukemia, with its specific expression patterns being observed in the inflammatory meta program." (PMID 38944814, 2024). "Alemtuzumab (anti-CD52, 3 μg/ml) was used as reference control since it is used for treatment of B cell chronic lymphocytic leukemia with manageable adverse events, also with respect to cytokine release." (PMID 40650770, 2025). "The monoclonal antibody Alemtuzumab combined with CD52 was used to treat chronic lymphocytic leukemia, multiple sclerosis and other autoimmune diseases." (PMID 38817869, 2024). "Alemtuzumab has historically been used in the treatment of chronic lymphocytic leukaemia and is now used in multiple sclerosis, because of its ability to deplete CD52+ lymphocytes." (PMID 39276679, 2024). "While it is known that CD52 expression in chronic lymphocytic leukemia and breast cancer has prognostic and predictive value, its significance in melanoma is unclear." (PMID 39274345, 2024). "Immunotherapeutic monoclonal antibody Alemtuzumab targets CD52 and is used in chronic lymphocytic leukemia (CLL) therapy." (PMID 36982699, 2023). "We previously generated a panel of mAbs capable of targeting hFcγRIIB, showing they enhanced anti-CD20 mAb-mediated depletion of both normal and malignant B cells in vivo, as well as anti-CD52 mAb-mediated depletion of chronic lymphocytic leukemia (CLL) cells." (PMID 35858562, 2022). "Alemtuzumab, an anti-CD52 monoclonal antibody was applied successfully to B cell chronic lymphocytic leukemia (B-CLL) patients since 2001, but was only secondarily tested in MCL without a break-through." (PMID 33668876, 2021). "The next biologics were approved early in the 21st century, with humanized monoclonal antibody alemtuzumab (Campath1), which targets CD52 on B, T and NK cells and monocytes, in the therapy of chronic lymphocytic leukemia (2001)." (PMID 33297561, 2020). "In the treatment of chronic lymphocytic leukemia, Alemtuzumab recognizes T cells with high expression of CD52, eliminates the disabled T cells through cell lysis, and restores the normal immune function of T cells." (PMID 33240323, 2020). "The antibody that inhibits CD-52 is known as Alemtuzumab, an IgG1k humanized antibody that binds to the CD-52 cell surface, which is indicated for chronic lymphatic leukaemia." (PMID 26270662, 2015). "Alemtuzumab (Campath) is a humanized anti-CD52 monoclonal antibody that is used predominantly for the treatment of refractory chronic lymphocytic leukemia (CLL) in adult populations and for graft versus host disease prevention in pediatric HSCT recipients." (PMID 24795859, 2014). "Alemtuzumab is a mAb targeted at the CD52 antigen, found on the surface of most chronic lymphocytic leukemia (CLL) cells." (PMID 22190975, 2011). "Alemtuzumab (MabCampath®) is a humanized, IgG1κ, monoclonal antibody directed against CD52, which was formerly clinically approved for treating chronic lymphocytic leukemia (CLL) and therefore regarded as an ideal candidate for further tests to develop new treatment options." (PMID 37108680, 2023). "In chronic lymphocytic leukemia, increased levels of CD52+ LMVs (CD52 is the most prevalent marker of peripheral lymphocytes) have been proposed as useful biomarkers for monitoring disease progression, and LMVs derived from B-cells for the prediction of treatment time and overall survival." (PMID 35740926, 2022). "Currently, IL-15 is being tested in combination with other mAbs directed against tumor-associated antigens, with Alemtuzumab (anti-CD52) in adult patients with T-cell leukemia (NCT02689453) and Obinutuzumab (anti-CD20) in patients with chronic lymphocyte leukemia (NCT03759184)." (PMID 32605193, 2020).
chronic lymphocytic leukemia (continued). "Universal CAR19T (UCART19) cells were generated using TALENs to target the constant region of the TCRα chain (TRAC) and the CD52 gene to make UCART19 cells resistant to Alemtuzumab (Campath®), which is an antibody used to eliminate CD52+ lymphocytes in B-cell chronic lymphocytic leukemia." (PMID 32903482, 2020). "Collectively these three host immune responses represent the major mechanism of selective anti-neoplastic cytotoxicity evoked by anti-CD20, anti-CD52 and similar monoclonal immunoglobulins utilized for the therapeutic management of haemopoietic neoplasias (e.g. chronic lymphocytic leukemia)." (PMID 25821636, 2015). "Alemtuzumab is an anti-CD52 monoclonal antibody that was initially approved by the FDA in 2001 for B-cell chronic lymphocytic leukemia (B-CLL)." (PMID 38022633, 2023). "Alemtuzumab is an anti-CD52 mAb, which is considered a single agent for treating B-cell chronic lymphocytic leukemia (B-CLL) by antibody-dependent cell-mediated lysis." (PMID 35664074, 2022). "Finally, alemtuzumab is a recombinant DNA-derived humanized IgG1 kappa mAb that is directed toward CD52 and is used is used to treat B-cell chronic lymphocytic leukemia (B-CLL) and multiple sclerosis patients, warranting consideration for the treatment of ABMR." (PMID 27818660, 2016). "Alemtuzumab (Campath) is an anti-CD52 mAb approved for use in B-cell chronic lymphocytic leukemia (B-CLL)." (PMID 24738036, 2014). "Alemtuzumab, a humanized monoclonal antibody targeting against CD52, is currently approved by the FDA for treatment of previously untreated patients with B-cell CLL." (PMID 40943476, 2025). "The antibody against CD52 (CAMPATH-1 antigen, a glycoprotein present on the surface of mature lymphocytes and inflamed monocytes and dendritic cells) has been traditionally used for treatment of B cell chronic lymphocytic leukemia." (PMID 39480497, 2024). "Universal anti-CD19 CAR T cells were developed by gene editing strategies to knock out the constant region of the TCRα chain and the CD52 gene, in order to make the CAR T cells resistant to an anti-CD52 antibody that is used for the treatment of B-cell chronic lymphocyte leukemia." (PMID 35008348, 2021). "In addition, most TEMs co-express the leukocyte marker CD52, which is the target of alemtuzumab, a monoclonal antibody approved by the Food and Drug Administration (FDA) for the treatment of chronic lymphocytic leukemia." (PMID 35011579, 2021).
multiple sclerosis (30 papers, 2015 to 2025). A progressive autoimmune disorder affecting the central nervous system resulting in demyelination. "CD52 is also used as target with anti-CD52 gene to reduce the severity of associated symptoms to multiple sclerosis." (PMID 35371081, 2022). "Cases of neurological autoimmunity including antibody-associated encephalitis has been reported in multiple sclerosis patients treated with the CD52 (e.g., alemtuzumab) or CD25 (e.g., daclizumab) protein inhibitors." (PMID 34305787, 2021). "Interestingly, rs2523608 has been reported to be negatively associated with the binding antibody response to interferon beta-1a (IFN beta-1a) therapy in multiple sclerosis (MS), which shares common pathogenic processes with CD52." (PMID 40087274, 2025). "However, this occurred in the context of treatment of multiple sclerosis with the monoclonal anti-CD52 antibody alemtuzumab, which is associated with significant immune suppression due to profound B- and T-cell depletion." (PMID 37715128, 2023). "Alemtuzumab, a humanized monoclonal antibody, attenuates multiple sclerosis progression through CD52‐targeted depletion of T and B cells, thereby reducing central nervous system inflammation and demyelination." (PMID 40260643, 2025). "Alemtuzumab is a powerful anti-CD52 drug that is an established treatment option in patients with multiple sclerosis due to its proven efficacy." (PMID 40440332, 2025). "Antibody against CD52 (alemtuzumab) has shown good effects for treatment of multiple sclerosis and asthma in clinical trials and colitis in an experimental mouse model." (PMID 39480497, 2024). "Alemtuzumab selectively binds to CD52 molecules on the surface of B cells and T cells, inhibits abnormal activation of lymphocytes, and, thereby, delays the occurrence of multiple sclerosis." (PMID 39194690, 2024). "Background and objectives: alemtuzumab is a monoclonal anti-CD52 antibody acting on B and T cells in highly active multiple sclerosis (MS)." (PMID 36902555, 2023). "Antibodies against CD52 have been used to decrease the level of surface antigen and treat multiple sclerosis and its murine model experimental autoimmune encephalomyelitis (EAE)." (PMID 35720411, 2022). "This is the case for instance of alemtuzumab, a humanized monoclonal Ab that targets CD52+ cells, in patients with multiple sclerosis." (PMID 34036513, 2021). "Anti-cluster of differentiation 52 (CD52) monoclonal antibody (mAb) has been employed in the treatment of chronic lymphoblastic leukemia and multiple sclerosis." (PMID 34669957, 2021). "Alemtuzumab (anti-CD52 mAb) leads to a long-lasting disease activity suppression in patients with relapsing forms of multiple sclerosis (MS)." (PMID 33133074, 2020). "It was shown that an antibody against CD52 can effectively deplete CD52-expressing cells for the treatment of multiple sclerosis (a humanized monoclonal antibody called Alemtuzumab is used) or in a mouse model (experimental autoimmune encephalomyelitis)." (PMID 31362699, 2019). "The authors would like to thank the support of the Medical Research Council, the Multiple Sclerosis Society and work relating to CD52 was supported by Genzyme Corporation, a Sanofi company." (PMID 27925187, 2017). "Anti-CD52 targeting is a very promising therapy for B cell malignancies and autoimmune diseases including rheumatoid arthritis and multiple sclerosis; however, the current standard treatment, alemtuzumab, produces ADAs in a high frequency of patients." (PMID 26372145, 2015). "Notably, CD52 is the therapeutic target of alemtuzumab, which is approved for the treatment of multiple sclerosis." (PMID 35634297, 2022). "Although little is known about its exact physiological function, CD52 has shown to be a promising target for several immune system-mediated diseases, such as multiple sclerosis (MS), autoimmune inflammatory neurodegenerative diseases, allergic asthma, and lymphocytic leukemia." (PMID 36468029, 2022).
multiple sclerosis (continued). "Alemtuzumab, a polyclonal antibody targeting CD52 on T and B cells, has been approved by the FDA for the treatment of leukemia and multiple sclerosis." (PMID 39194690, 2024). "Alemtuzumab, an anti-CD52 depletion antibody, is already FDA-approved for the treatment of multiple sclerosis and has potential for use in the treatment of acute lymphoblastic leukaemia and myeloid leukaemia." (PMID 37173673, 2023).
leukemia (18 papers, 2009 to 2025). A malignant (clonal) hematologic disorder, involving hematopoietic stem cells and characterized by the presence of primitive or atypical myeloid or lymphoid cells in the bone marrow and the blood. "Our findings suggest the possibility of a new therapeutic option, the anti-CD52 antibody alemtuzumab, to treat leukemia carrying the FLT3-ITD mutation." (PMID 34035227, 2021). "Magnetic NPs coated with EpCAM and CD52 antibodies are used as ligands to bind with targets of prostate, colon, lung, or pancreatic cancer or leukaemia." (PMID 38112935, 2023). "Taken together, the findings of this study revealed CD52 as a molecular target for the antibody treatment of FLT3-ITD leukemia." (PMID 34035227, 2021). "High levels of CD52 expression have been observed in lymphoma and leukemia, and CD52 may play a role in the growth and survival of cancer cells." (PMID 36982699, 2023). "Our study found that CD52 was widely expressed in leukemia cells and all types of immune cells." (PMID 36033493, 2022). "Additionally, CDC induction plays important roles in alemtuzumab (CD52) therapy for leukemia and the combined therapy with trastuzumab and pertuzumab (anti-HER2/neu) for breast and gastric cancers." (PMID 36575233, 2022). "Moreover, it is now possible to detect antibodies present in leukemia cells, such as CD52, CD38, CD33, CD20, CD25, CD19, and CD22, and target them with new antibody–drug conjugates." (PMID 35011701, 2022). "We successfully prepared CD52 CAR-T cells with anti-leukemia effects, which might provide the foundation for further immunotherapy." (PMID 35680625, 2022). "Although the function of soluble CD52 is uncertain, but it seems that CD52 may be involved in migration and activation of T-cells, leukemia and autoimmune diseases." (PMID 33705353, 2021). "Intravenously administered alemtuzumab, a monoclonal antibody against the CD52 antigen, successfully reduced leukemia cells in peripheral blood; however, intrathecal treatment with methotrexate, cytarabine, and prednisone had a limited effect on the CNS involvement." (PMID 32802528, 2020). "The standard front-line therapy against this leukemia (fludarabine, cyclophosphamide, and rituximab), as well as the current alternative treatments (e.g., anti-CD52, optimized anti-CD20, and anti-CD23 antibodies), can generate refractoriness or undesirable side effects." (PMID 25734483, 2015). "The gene most strongly induced by EVI1 in this system was CD52, which has previously been shown to be up-regulated by EVI1 and proposed as an immunotherapeutic target for EVI1-positive leukemia." (PMID 25886616, 2015). "In fact, an anti-human CD52 antibody therapy, Alemtuzumab (Campath) has been developed and is FDA approved for the treatment of CD52 expressing leukemia." (PMID 19545375, 2009).
lymphoma (18 papers, 2008 to 2025). A malignant (clonal) proliferation of B- lymphocytes or T- lymphocytes which involves the lymph nodes, bone marrow and/or extranodal sites. "This study also demonstrated in vivo anti-tumor activity of the TCR/CD52-deficient CAR-T cells in a lymphoma murine model." (PMID 33514392, 2021). "If CD52 is a negative regulator for aggressive B-cell lymphoma, targeting CD52 will directly accelerate malignant transformation of lymphoma, such as extranodal dissemination." (PMID 37700827, 2023). "rhG-CSF plus the monoclonal anti-CD52 antibody (Alemtuzumab) increased survival from 60% to 100% at 12 weeks in a mouse lymphoma model." (PMID 30814617, 2019). "In support of such efforts, here we perform CD52 target validation on a series of double-hit (n = 40) and double-expressor (n = 58) lymphomas using immunohistochemistry." (PMID 30020951, 2018). "CD52 expression levels varied considerably across samples, however positive staining was observed in 75% of both double-hit and double-expressor lymphomas." (PMID 30020951, 2018). "Advantages and disadvantages of conventional CD20/CD30/CD52-targeted therapy for lymphoma." (PMID 40703518, 2025). "However, the exact roles and specific functions of FHIP2B, POMT1, TTLL3, CROCC, and CD52 in lymphoma and the molecular mechanisms of their downmodulation upon MyD88L265P expression are not yet fully understood and require further research." (PMID 36982699, 2023). "As a proof of application of this platform, TCR/CD52-deficient CAR T cells were administered concurrently with alemtuzumab and demonstrated antitumor activity in a lymphoma murine model similar to unmodified anti-CD19 CAR T cells, with resistance to alemtuzumab destruction." (PMID 32296011, 2020). "Several antibodies have been developed for T cell NHL (e.g., alemtuzumab (anti-CD52), brentuximab (anti-CD30), and mogalizumab (anti-CXCR4)), all of which mediate at least part of their anti-lymphoma efficacy through ADCC." (PMID 35258793, 2022). "Alemtuzumab is a mAb approved for clinical use that binds CD52, which is a GPI-anchored glycoprotein expressed on the surface of lymphoma cells." (PMID 18366248, 2008). "The antibody alemtuzumab was used as a tool compound for the first screening approach as several types of lymphoma downregulate CD20 expression but not CD52 expression, also seen in hMB cells." (PMID 39603243, 2024). "Meanwhile, CD52 and SSPN, as membrane proteins, probably directly participate in the interaction between lymphoma cells and tumor microenvironment and finally determine lymphoma dissemination." (PMID 37700827, 2023). "In the ongoing ALPHA2 study (NCT04416984), patients with r/r lymphoma receive either a single or consolidation dose of ALLO-501A, which uses Cellectis technologies to disrupt the T cell receptor alpha gene (TRAC) and the CD52 gene." (PMID 36009506, 2022). "Compared to the other clusters, cluster 5 expressed least CD52, a favored target for lymphoma therapy, and contained the highest amount of non-cycling cells assigned to G1." (PMID 33668876, 2021). "As nearly all studies investigating CD52 expression by aggressive B-cell neoplasms were performed prior to the establishment of our current working definitions of DHL and DEL, such studies failed to differentiate these more aggressive lymphomas from conventional DLBCL." (PMID 30020951, 2018).